LPCAT2 (lysophosphatidylcholine acyltransferase 2)
Diseases named in the same sentence as LPCAT2 in open-access papers (continued):
Sharing a sentence is not in itself a finding about the gene and the disease.
esophageal tumors (1 paper, 2020). "The results further confirmed that angustoline suppressed esophageal tumors through regulating LKB1/AMPK/ELAVL1/LPCAT2 and consequently inhibiting the excessive conversion from LPC (16:0) to PC (16:0/18:1)." (PMID 32733803, 2020). "However, the role of LPCAT2 in esophageal tumor model was rarely reported." (PMID 32733803, 2020). "Therefore, LKB1, AMPK, ELAVL1, and LPCAT2 were chosen as the possible candidate factor in esophageal tumor models in our study, their roles in the growth and development of esophageal tumor, as well as the effect of angustoline on their expression levels, were investigated." (PMID 32733803, 2020). "Additionally, KYSE450 tumor bearing mouse model was constructed, the role of angustoline in inhibiting esophageal tumors through regulating LKB1/AMPK/ELAVL1/LPCAT2 pathway was validated, and found that the conversion from LPC (16:0) to PC (16:0/18:1) was blocked by angustoline in some degree." (PMID 32733803, 2020). "Considering the study on the effects of angustoline on esophageal tumor was rarely reported, the present manuscript investigated anti-tumor role of angustoline in vitro and in vivo, and explored the regulation of angustoline in LKB1/AMPK/ELAVL1/LPCAT2 pathway and phospholipid remodeling." (PMID 32733803, 2020).
glioblastoma (1 paper, 2023). The most malignant astrocytic tumor (WHO grade IV). "In particular, AGPAT5, AGPAT6/GPAT4, AGPAT8/ALCAT1/LCLAT1, AGPAT9/LPCAT1, and AGPAT11/LPCAT2 show higher expression in glioblastoma tumors than in healthy tissue." (PMID 37046844, 2023). "In glioblastoma, there is increased expression of AGPAT5, AGPAT9/LPCAT1, and AGPAT11/LPCAT2 compared to healthy brain tissue." (PMID 37046844, 2023).
Granuloma (1 paper, 2026). A compact, organized collection of mature mononuclear phagocytes, which may be but is not necessarily accompanied by accessory features such as necrosis. "Using this spatially-integrated approach, we identified LPCAT2-mediated membrane re-modelling of myeloid cells as a novel feature of these granulomas." (PMID 41862629, 2026).
hepatoma (1 paper, 2014). "Since double KDs are difficult and phenotypes are weak due to mutual compensation by the isoenzymes, we also analyzed the human hepatoma cell line HuH7, which expresses LPCAT3 and LPCAT1, but no LPCAT2." (PMID 25491198, 2014).
lung carcinoma (1 paper, 2015). "Whereas, other proteins, such as LPCAT2 that is highly expressed in inflammatory cells, BPIFA3 that is highly expressed in lung cancer, PPIA that activates NFkB pathway, and FABP4 that has pro-angiogenic role, were downregulated in SBP1 overexpression xenograft tumors." (PMID 25974208, 2015).
mastitis (1 paper, 2023). Inflammation of breast tissue during lactation or postpartum due to an obstructed duct or infection. "In this study, the ZRANB3, PIAS1, ACTR3, LPCAT2, MGAT5, and SLC37A2 genes in Xinjiang brown cattle, which are associated with mastitis resistance, were identified using a GWAS." (PMID 37372369, 2023). "These six genes (ZRANB3, PIAS1, ACTR3, LPCAT2, MGAT5, and SLC37A2) are all potentially associated with mastitis resistance." (PMID 37372369, 2023).
non-alcoholic steatohepatitis (1 paper, 2020). "In a recent study of western diet-associated non-alcoholic steatohepatitis, LPCAT1 and LPCAT2 are in the top 10 liver genes/transcripts most significantly elevated in mice fed western style diets compared to standard diets." (PMID 32429496, 2020).
peripheral nerve injury (1 paper, 2012). Injury to a peripheral nerve. "In the present study, we demonstrated that LPCAT2 mRNA was expressed in microglia and neurons, and PAFr mRNA induced by peripheral nerve injury was exclusively co-localized with microglia in the spinal cord." (PMID 22296727, 2012).
pneumonia (1 paper, 2024). An acute, acute and chronic, or chronic inflammation focally or diffusely affecting the lung parenchyma, caused by an infection in one or both of the lungs (by bacteria, viruses, fungi, or mycoplasma.). "Moreover, LPCAT2 has been implicated as a biomarker for inflammatory disorders such as cedar pollen allergenic rhinitis, pneumonia, and pulmonary tuberculosis." (PMID 38785798, 2024).
prostate adenocarcinoma (1 paper, 2020). "Finally, data from TCGA supports the function of rs2241145 and rs17301608 as eQTLs on LPCAT2 expression in prostate adenocarcinoma." (PMID 32751332, 2020).
steatosis (1 paper, 2017). Increased lipid within the cytoplasm of cells. "Using immunohistochemistry, we found higher staining for LPCAT2 protein in zone 1 for WT mice and in zone 3, particularly around regions of steatosis, for ob/ob mice." (PMID 27863448, 2017).
tumor (14 papers, 2014 to 2025). "As a consequence, a higher tumor expression of LPCAT2 is associated with a worse prognosis for colorectal cancer patients." (PMID 38893234, 2024). "Functionally, LPCAT2 overexpression significantly inhibits cell proliferation and colony formation in vitro, while repressing tumor growth and Ki67 expression in vivo." (PMID 41450739, 2025). "Conversely, LPCAT2 downregulation enhances proliferative capacity in vitro and stimulates tumor growth and Ki67 in vivo." (PMID 41450739, 2025). "In this study, we identified LPCAT2+ tumor cell populations with less malignancy than LPCAT2- tumor cells in human and mouse CRC tissues using scRNA-seq." (PMID 38605214, 2024). "LPCAT2 overexpression repressed tumor growth compared to control, and also downregulated the expression level of proliferation marker Ki67." (PMID 38605214, 2024). "Numerous studies increasingly suggested that LPCAT2 acted as either an oncogene or a tumor suppressor in a cell-type and context-specific manner." (PMID 38605214, 2024). "Other observations suggested a tumor-suppressive role for LPCAT2 in certain cancer types, such as papillary thyroid cancer." (PMID 38605214, 2024). "To explore the molecular mechanisms underlying the tumor suppressive role of LPCAT2, we conducted RNA-sequencing analysis to identify differentially expressed genes (DEGs) in CRC cells overexpressing LPCAT2." (PMID 38605214, 2024). "We identified a subpopulation of LPCAT2+ tumor cells via scRNA-seq analysis, which had a lower CNV score than LPCAT2- tumor cells." (PMID 38605214, 2024). "In vivo experiments in CT26 tumor-bearing mice confirmed that LPCAT2 overexpression favors tumor progression and resistance to FOX." (PMID 37627128, 2023). "Specifically, increased LPC acyltransferase (LPCAT1, LPCAT2) activities in neoplastic tissues have been proposed to confer tumor resistance through elevated PC production." (PMID 32733643, 2020). "Correspondingly, LPCAT2 was also increased in these cells and was recognised as a biomarker of tumour metastasis in HNSCC." (PMID 32020064, 2020). "To evaluate the impact of LPCAT2-mediated LD production on tumour cell growth in vivo, we generated a mouse CRC cell line (CT26) overexpressing or not LPCAT2." (PMID 29358673, 2018). "Lpcat2 knockdown (shLpcat2 #2 and #4) resulted in a slight reduction in tumour progression under FOX therapy as compared to shneg tumour-bearing mice, but was associated with significantly increased mouse survival." (PMID 29358673, 2018). "The amount of an inducible PAF synthesis enzyme, lysophosphatidylcholine acyltransferase 2 (LPCAT2) protein significantly increased in the spinal cord after transplantation of NCTC 2472 tumor cells into mouse tibia." (PMID 24637403, 2014). "These profound differences in molecular drivers, metabolism, tumor microenvironment, and cellular functions highlight the need for distinct, side-specific therapeutic strategies, such as targeting the LPCAT2/ferroptosis axis or MMP7+ cells in LCRC, and glycolysis or hypoxia in RCRC." (PMID 41450739, 2025). "Furthermore, findings uncovered that LPCAT2 acts as a tumor suppressor through a novel ferroptosis-inducing PRMT1/SLC7A11 signaling axis." (PMID 41450739, 2025). "We established LPCAT2 low expression SW480 cell line-derived xenograft (CDX) tumor models." (PMID 38605214, 2024). "Hence, lysophosphatidylcholine acyltransferase 2 or LD biogenesis inhibitors significantly improves tumor regression induced by the dual chemotherapy and mice survival." (PMID 35945203, 2022). "To date, few studies have investigated the function of LPCAT2 in tumor biology." (PMID 33392068, 2020). "Moreover, the fact that tumour growth was potentiated by LPCAT2 overexpression in basal conditions strengthened the role for immune tumour microenvironment modulation in tumour expansion." (PMID 29358673, 2018).
tumor (continued). "Collectively, these data highlight a yet undescribed direct role of LD accumulation in CRC cell chemoresistance and suggest a new model in which the LPCAT2 expression profile could discriminate between responsive and resistant tumour cells." (PMID 29358673, 2018). "Moreover, further studies in larger patient cohorts would be required to fully assess the prognostic and predictive value of LPCAT2/LD considering tumour genetics." (PMID 29358673, 2018). "The expression of AGPAT11/ LPCAT2 reflected the tumor grade." (PMID 25415055, 2014). "Finally, LPCAT2 has potential pro-tumor functions in prostate cancer." (PMID 38893234, 2024). "Moreover, inhibitors of the PRMT1/SLC7A11 axis could delay tumor progression in CRC with low LPCAT2 expression, making it a potentially effective treatment for CRC." (PMID 38605214, 2024). "Indeed, in CRC cells, the increased in LD production mediated by lysophosphatidylcholine acyltransferase 2 confers resistance to 5-fluorouracil combined with oxaliplatin, by preventing ER stress-induced apoptosis and reducing the tumor-infiltrating CD8+ T cells." (PMID 35945203, 2022). "Results showed that the levels of AMPK and LKB1 in a large majority of the tumor samples were lower than the normal controls, the levels of ELAVL1 and LPCAT2 in tumor samples were higher than the normal control (p < 0.05)." (PMID 32733803, 2020). "The FOX regimen induced TIM3+ PD1+ subpopulation accumulation in control grafts as compared to LPCAT2-overexpressing grafts, thus suggesting that chemotherapy only activates a CD8+ immune response in control tumours." (PMID 29358673, 2018). "The amount of LPCAT2 protein significantly increased in the spinal cord at 8, 15 and 30 days after transplantation of NCTC 2472 tumor cells into mice tibia." (PMID 24637403, 2014). "We identified a population of LPCAT2-positive (LPCAT2 + ) tumor cells with a lower CNV score than LPCAT2-negative (LPCAT2-) population." (PMID 38605214, 2024).
cancer (12 papers, 2018 to 2024). A tumor composed of atypical neoplastic, often pleomorphic cells that invade other tissues. "In relation to cancer, LPCAT2 has been reported to have either oncogenic or cancer-suppressive effects in various cancer types." (PMID 38605214, 2024). "Lysophosphatidylcholine acyltransferase 2 (LPCAT2) induces LD accumulation in cancer patients during the onset of chemoresistance." (PMID 35927287, 2022). "LPCAT2-driven LD biogenesis was shown to protect cancer cells from this chemotherapy-induced ER stress and cell death in vivo and in vitro." (PMID 34581907, 2021). "The study revealed that LPCAT2 increases the resistance of cancer cells to immunogenic cell death and mediates chemoresistance by promoting the antiapoptotic response to endoplasmic reticulum stressors." (PMID 35155562, 2021). "In this model, the high-LPCAT2 cancer cell phenotype under anticancer agent treatments such as the FOX regimen, produces more LDs to maintain ER homeostasis, sequester CRT and impair ICD." (PMID 29358673, 2018). "Besides, EGFR can induce the expression of the PAF receptor, which can be activated by the PAF produced by LPCAT2 in EGFR-expressing cancer cells, in an autocrine mechanism, or surrounding cells in the microenvironment, in a paracrine fashion." (PMID 33392068, 2020). "However, the role of LPCAT2 in cancer progression remains controversial." (PMID 38605214, 2024). "Thus, they function as cancer-promoting genes, such as FOXQ1, PHLDA2, LPCAT2, AP1S3, and EPS8." (PMID 32977589, 2020).
infection (3 papers, 2016 to 2025). The state of being infected such as from the introduction of a foreign agent such as serum, vaccine, antigenic substance or organism. "Regulatory enzymes related to phospholipid remodeling, namely, Lpcat1, Lpcat2, and Mboat1, are also upregulated upon infection." (PMID 40463366, 2025). "In the infection group, the expression of Alox5 and Cox-2 was upregulated significantly, and the regulatory enzymes Lpcat1 and Lpcat2, which are involved in PC remodeling, were also significantly upregulated." (PMID 40463366, 2025). "In contrast, the LPCAT2 activation values were reduced to 35.65 % at 5 min post-infection in JAK2-inhibited cells." (PMID 27098179, 2016). "As a result, B. abortus infection and PAF stimulation resulted in notable increase in the values of LPCAT2 activation by 53.63 % at 5 min post-infection compared to resting cells." (PMID 27098179, 2016). "Additionally, the expression of Lpcat1 and Lpcat2 increased after infection." (PMID 40463366, 2025).
bacterial infection (1 paper, 2024). "Lipidomic, proteomic, and genomic analysis would be beneficial for better understanding the influence of LPCAT2 on macrophage inflammatory response to bacterial infection." (PMID 38785798, 2024). "This study provides novel evidence that the influence of LPCAT2 on macrophage inflammatory response to bacterial infection depends on the LPS serotype, and it supports previous evidence that LPCAT2 regulates inflammatory response by modulating protein translocation to lipid rafts." (PMID 38785798, 2024).
LPCAT2 also shares sentences with these, for which no sentence is quoted: colitis (2 papers); acute lung injury (1); allergies (1); asthma (1); clear-cell renal cell carcinoma (1); neurological diseases (1); ovarian carcinoma (1); pulmonary tuberculosis (1); thyroid cancer (1); visceral leishmaniasis (1).